MYC (MYC proto-oncogene, bHLH transcription factor)
Diseases named in the same sentence as MYC in open-access papers (continued):
Sharing a sentence is not in itself a finding about the gene and the disease.
cancer (continued). "LncRNAs can also bind to major metabolic regulatory proteins, such as MYC, and form feedback loops that increase glycolysis and other metabolic shifts associated with cancer biomass." (PMID 41154428, 2025). "Another peculiarity is the fact that MYC is rarely mutated in cancers, where direct amplification of the MYC locus represents the most apparent form of its genetic alteration." (PMID 41561634, 2025). "MYC is a transcription factor and a classic oncogene, with mutations closely associated with the development of various cancers." (PMID 41282023, 2025). "Mechanistically, SP140 mutations caused downregulation of BCR signaling and MYC targets, leading to cancer progression and poor prognosis." (PMID 41188771, 2025). "DHX15 has also been implicated in cancer, through its role in splicing and because it binds proteins like c-MYC." (PMID 40168451, 2025). "Only 6 CDGs appeared under cell cycle and those were ANAPC13, ANAPC5, MAD2L2, GADD45G, CCND2, and surprisingly MYC — a gene often implicated as a cancer driver." (PMID 39774001, 2025). "GSEA based on the cancer hallmark gene sets revealed significant inhibition of E2F targets, MYC targets, G2M checkpoint, Notch signaling, and mitotic spindle pathways in SLC7A1-knockdown IOMM-Lee cells." (PMID 41184266, 2025). "Increased MYC activity or MYC amplification is widespread in human cancers and is causally associated with tumorigenesis and poor clinical outcomes." (PMID 39851497, 2025). "Dysregulation of c-MYC expression, often through gene amplification or chromosomal translocation, is implicated in numerous human cancers, underscoring its significance as both a critical regulator of normal cellular processes and a potent oncogene." (PMID 40666093, 2025). "The oncogenic power of MYC stems from its ability to control the expression of genes associated with diverse cellular processes that, when improperly constrained, promote cancer initiation, progression, and maintenance." (PMID 40647552, 2025). "Consistently, MYC and genes within the CoA-isoprenoid axis display strong association with clinical outcomes in human cancers." (PMID 40832336, 2025). "In previous studies, the MYC oncogene was found to be overexpressed in a variety of cancers and associated with poor outcomes." (PMID 38240704, 2024). "Further, high expression levels of MYC have been associated with particularly aggressive cancers, which are summarized in a review." (PMID 38731892, 2024). "RAS and MYC rank amongst the most commonly altered oncogenes in cancer, with RAS being the most frequently mutated and MYC the most amplified." (PMID 39164274, 2024). "Due to its involvement in reprogramming cellular metabolism, MYC is believed to be a hallmark of cancer progression that maintains the rapid proliferation of cancer cells." (PMID 38862581, 2024). "RPs and ribosome biogenesis (RiBi) are targets of MYC and are associated with cancer and, specifically, OS onset and progression." (PMID 39596100, 2024). "A number of cancers exhibit enhanced invasiveness caused by the c-MYC oncogene, and it plays an essential role in cancer progression." (PMID 38240704, 2024). "In advanced cancer cells, radiation and chemotherapy cause genomic instability, which oncogenic MYC compensates for by developing a highly efficient DNA repair system." (PMID 39563886, 2024). "PDS1 tumors displayed elevated cell-cycle-related pathways, including MYC and E2F targets and G2M checkpoint, whereas there was near universal repression of cancer-associated hallmark signaling in PDS3." (PMID 38351382, 2024). "The aberrant expression of proto-oncogenes, particularly the overexpressed c-MYC gene in 70% of cancer cells, is intimately linked to the development of tumors." (PMID 39338293, 2024).
cancer (continued). "Gene set enrichment analysis (GSEA) showed that FOXA1 knockout resulted in the enrichment of cancer hallmark signatures including E2F targets, MYC targets and NOTCH signaling, and other molecular events including cell cycle, DNA replication and keratinization." (PMID 39687207, 2024). "c-Myc (MYC) is a carcinogenic transcription factor closely linked to cancer cell reprogramming and resistance to chemotherapy." (PMID 39598829, 2024). "Reintroducing the let-7b mimic has been scientifically demonstrated to successfully suppress the cancer-causing gene c-MYC and effectively counteract the resistance to multiple drugs in gastric cancer." (PMID 38836981, 2024). "Because of its multifaceted dysregulation, MYC-driven cancers are often associated with poor prognosis." (PMID 38390324, 2024). "Although more traditionally linked with cancer, MYC is also important in brain development and function." (PMID 39385284, 2024). "Targeting CDK9 induces acute loss of MYC expression and potent cell apoptosis in many cancer models, and it has been reported to induce vulnerability in ibrutinib-resistant MCL cells." (PMID 38326887, 2024). "MYC (also known as c-Myc) is a transcription factor overexpressed in over 70% of human cancers, which is associated with poor patient survival." (PMID 38778217, 2024). "KRAS, a frequently mutated oncogenic protein in human cancers, plays a pivotal role in regulating MYC and mTOR activity through RAF-MEK-ERK and PI3K-AKT pathways, respectively." (PMID 38218942, 2024). "The regulation of cell growth, proliferation, and survival in cancers is associated with the molecular interactions between the MYC gene and PTEN." (PMID 38756697, 2024). "The MYC gene is one of the most frequently dysregulated oncogenes implicated in the initiation, progression, and advancement of various cancers." (PMID 39949609, 2024). "Correlation analysis showed that PVT1 was associated with several pathways related to cancer progression, and MYC targets showed the strongest positive association." (PMID 39376555, 2024). "We provide evidence underscoring the pivotal role of the CREPT-mediated association of MYC-MAX with RNAPII in cancer development." (PMID 39615685, 2024). "Deregulated expression of c-MYC protein is observed in a wide range of human cancers and is particularly associated with aggressive disease and poor clinical outcomes." (PMID 39830506, 2024). "The loss of c-MYC increased active caspase 7, leading to the impaired migration of these cancer cells." (PMID 39123391, 2024). "Signaling cascade molecules, including pERK, pSTAT3, and MYC have all been implicated in promoting EZH2 transcriptional activation in different cancers." (PMID 38339397, 2024). "In this study, we explored the relationship between aging and DNA repeat-mediated genetic instability in vivo using an H-DNA-forming mirror-repeat sequence from the cancer-associated human c-MYC gene." (PMID 39595629, 2024). "Co-IP assays confirmed that USP45 binds directly to MYC, selectively removing K48-linked ubiquitin chains from MYC, thereby intensifying Dox resistance in cancer cells." (PMID 38702734, 2024). "Specifically, we target mutations within two key oncogenic molecules, PAX5 and MYC, aiming to elucidate their role in triggering cancer cell death using the CRISPR-Cas9 system." (PMID 39469218, 2024). "Targeting MYC has high potential therapeutic value due to its wide role in cancer development, its overexpression in varied cancers (approximately 70% of cancers), and its association with a poor prognosis." (PMID 38200580, 2024).
cancer (continued). "Deregulation of MYC gene expression and c-Myc protein levels have been associated with numerous diseases including cancer." (PMID 39482742, 2024). "These lncRNAs function independently of MYC, highlighting the complexity and significance of this genomic region in cancer biology and risk stratification." (PMID 38756785, 2024). "Cancer hallmark signatures including E2F targets, MYC targets and PI3K-AKT-MTOR, molecular events including cell cycles and DNA replication, were also found highly enriched in FOXM1 + sgFOXA1 cells." (PMID 39687207, 2024). "HPV viral integration has been associated with MYC activation in multiple cancer types; however, there have been mixed data on the prognostic significance of HPV integration." (PMID 38505587, 2024). "Together, these results indicate that MYC-driven cancer cells are exposed to diverse causes of RS owing to their multifunctional roles." (PMID 39456601, 2024). "Genetically engineered mice with the RAS and MYC OCGs show the combined effect of two cancer‐causing genes." (PMID 38827026, 2024). "In line with this, RNA-seq data showed that the combination treatment dramatically downregulated cancer hallmark signatures including MYC targets, E2F targets and MTORC1 signaling." (PMID 39687207, 2024). "While MYC expression in KRAS-mutant cancers was associated with sensitivity to a SUMOylation inhibitor, our limitations are that we used a biased approach to the analysis and were unable to define a cut-off value for MYC expression." (PMID 38992694, 2024). "Being a “master regulator” of cellular metabolism and cancer progression, c-MYC is among the most significant transcription factors in numerous types of cancer cells that are associated with reprogramming, proliferation, and resistance to chemotherapy." (PMID 39346921, 2024). "Given the regulatory relationship between NCAPG2 and c-MYC, and aberrant c-MYC overexpression has been linked to cancer cell stemness, we further explored the potential role of NCAPG2 in PCa-CSCs." (PMID 38166947, 2024). "Pancancer analysis across the 33 cancers of The Cancer Genome Atlas (TCGA) identified focal amplification (28% of the samples) in at least one of the three MYC families, and MYC antagonists were mutated (MGA, 4% of samples) or deleted (MNT, 10% of samples)." (PMID 39456601, 2024). "The overexpression of c-MYC is implicated in many cancers, and it drives the tumors’ aggressiveness and metastatic progression, but there is no clinically approved drug that targets MYC." (PMID 39123391, 2024). "MYC largely functions as a transcription factor that coordinates many biological processes associated with the features of cancer, including autonomous proliferation and growth, increased protein biogenesis, and global changes in cellular metabolism." (PMID 39456601, 2024). "Consistent with the oncogenic role of TP63 in SCC, genes positively correlated with TP63 expression were enriched in cancer-promoting hallmark pathways, including E2F targets, G2M checkpoint, MYC targets and mTOR signaling pathways." (PMID 38509096, 2024). "Here, the authors show that nudix hydrolase 1 (NUDT1) is a MYC-driven metabolic vulnerability and generate a NUDT1 protein degrader to treat preclinical MYC-associated cancer." (PMID 38493213, 2024). "Especially interesting finding was that the DUSP6 knockdown cells displayed a gene expression pattern linked to dormant cancer cells such as inhibition of MYC, E2F1 targets, and the PI3K/AKT/mTOR signaling, as well as activation of the interferon response." (PMID 38886591, 2024). "It has already been described that MYC overexpression or dysregulation is associated with resistance to numerous cancer therapies, including chemotherapy, targeted therapy, and immunotherapy." (PMID 39164274, 2024). "Here, we create a genetically encoded label-free sensorto identify the interaction between a motif of the MYC transcriptionfactor, a primary cancer driver, and WDR5, a chromatin-associatedprotein hub." (PMID 39049818, 2024).
cancer (continued). "In cancer, c-MYC is frequently overexpressed or mutated, resulting in sustained activation, which drives uncontrolled cell proliferation." (PMID 39414766, 2024). "MYC activation is a known hallmark of cancer as it governs the gene targets involved in various facets of cancer progression." (PMID 38390324, 2024). "MYC gene family is a group of genes most widely investigated and implicated in the formation, maintenance, and progression of several different cancer types, such as breast cancer, lymphoma, and prostatic cancer." (PMID 39264149, 2024). "In this review, we discuss several articles reporting how herbal medicines can function as modulators of immune checkpoints, mediating MYC-associated cancer oncogenes to optimize immunometabolism, with fewer side effects and better prognosis." (PMID 37450923, 2024). "These genes are found in multiple hallmark pathways (allograft rejection, MYC targets, E2F targets, etc.)that have been associated with cancer initiation and progression, especially in hematologic malignancies." (PMID 38715059, 2024). "Functional analyses revealed that the “DNA repair” and “MYC targets v1” pathways as well as the infiltrations of several immune cells were significantly associated with CSscores of cancer patients." (PMID 39141443, 2024). "EMT-related signatures were more strongly correlated with non–cancer cell type signatures (e.g., T-cell and B-cell) than with cancer-associated processes (e.g., proliferation, and MYC activation)." (PMID 38349551, 2024). "Oncogene-Related Condensates: The dysregulation and heightened expression of MYC transcription factors, including MYC itself, are implicated in the majority of human cancers." (PMID 39777266, 2024). "BET inhibitors are being explored as treatments for a range of cancers, particularly those associated with MYC dysregulation." (PMID 38674385, 2024). "This pattern extends to the cancer stem cell biomarkers LGR5 and the transcription factor c-MYC, which are universally associated with cancer stem cells (CSCs)." (PMID 38339195, 2024). "Of note, across various cancers, MYC amplification is often associated with upregulation of BCL-XL and MCL-1, rescuing cells from MYC-induced apoptosis." (PMID 38942989, 2024). "MYC protein, a transcription factor encoded by the MYC proto-oncogene, is one of the most frequently activated oncoproteins playing important roles in cellular physiology of cancer." (PMID 37151387, 2023). "Synthetic lethality offers an alternative therapeutic strategy for the treatment of cancer by exploiting the vulnerabilities caused by MYC deregulation." (PMID 37443779, 2023). "MYC activity interference has been implicated in many malignant phenotypes of human cancers, including the Warburg effect." (PMID 36855123, 2023). "This indicated that elevated MYC expression in basal-like cancers in cluster 5 is caused by other mechanisms than gene amplification." (PMID 38111531, 2023). "The oncoprotein MYC is associated with poor clinical outcome in several cancer entities, including CNS tumors." (PMID 37183219, 2023). "The oncogene MYC is part of a superfamily of genes encoding the most commonly activated oncoproteins in human cancers." (PMID 36911524, 2023). "Several signaling pathways and key regulatory proteins including MYC are associated with cancer progression and metastasis." (PMID 37444499, 2023). "Mechanistically, CIII deficiency triggers presymptomatic cancer-like c-MYC upregulation followed by excessive anabolic metabolism and illicit cell proliferation against lack of energy and biosynthetic precursors." (PMID 37095097, 2023). "A similar finding has also been reported in cancer patients with colon liver metastases and MYC-amplified high-risk medulloblastoma." (PMID 36835173, 2023).
cancer (continued). "More than 70% of human cancers have abnormal MYC expression, which is associated with poor prognosis and aggressiveness." (PMID 37745860, 2023). "The transcription factor MYC plays a pivotal role in regulating various cellular processes and has been implicated in tumorigenesis across multiple cancer types." (PMID 37755397, 2023). "MYC gene is one of the most frequently deregulated oncogenes in many cancer types and a hallmark in the majority of human cancers." (PMID 36969025, 2023). "While the c-myc-335 WRE is well known for its role in CRC risk, the MYC gene is surrounded by several WREs implicated in the misregulation of MYC in many different kinds of cancer." (PMID 36423688, 2023). "MYC activation has been observed in numerous types of cancer, which results from genetic mutations, transcriptional regulation, and protein stabilization." (PMID 38049863, 2023). "Deregulation of MYC is implicated in 60%–70% of all human cancers, including Burkitt’s lymphoma, breast cancer, osteosarcoma, and hepatocellular carcinoma." (PMID 37908640, 2023). "The c-MYC proto-oncogene encodes for a transcription factor whereby expression is deregulated in many cancer types." (PMID 36979947, 2023). "c-MYC has been extensively associated with oncogenic functions, carcinogenesis, angiogenesis, chemoresistance, and many more cancer-promoting roles." (PMID 37624039, 2023). "A series of cancer-promoting pathways in the high-risk samples were upregulated, such as oxidative phosphorylation, MYC targets, and DNA repair." (PMID 36909185, 2023). "Across all cancers, high expression of MYC and ST6GALNAC4 together is associated with decreased survival (log-rank P < 1 × 10−10; HR = 2.1)." (PMID 36897988, 2023). "This is a 22‐nt‐long segment derived from the human c‐MYC promoter region which is frequently mutated in cancers." (PMID 37781931, 2023). "As deregulated MYC activity has been associated with the majority of human cancers, much of our understanding of MYC regulation comes from studies using cancer cell models." (PMID 37428010, 2023). "The 8q24 locus is enriched in cancer‐associated polymorphisms and, despite containing relatively few protein‐coding genes, it hosts the MYC oncogene and other genetic elements connected to tumorigenesis, including microRNAs (miRNAs)." (PMID 36366788, 2023). "KPNA2, a member of the nuclear transporter family, had recently been found to be involved in the nuclear entry of cancer stemness-associated transcription factor c-MYC." (PMID 37501099, 2023). "For example, m6A modification of the mRNA encoding MYC, a key oncogene, enhances its translation and subsequent protein expression, leading to increased migration and invasion of cancer cells." (PMID 37915034, 2023). "To investigate the impact of the HLH*-mediated defect in MYC mRNA translation, we selected a MYC driven cancer cell line in which to replicate the HLH* mutation and observe its impact on proliferation and cytotoxicity." (PMID 37768948, 2023). "The lncRNA MINCR has been demonstrated to be overexpressed in different cancers and to be significantly associated with the expression of the oncogene MYC." (PMID 37215074, 2023). "MYC is a transcription factor that is dysregulated in over 70% of human cancers where its overexpression is associated with poor patient outcomes (18, –20)." (PMID 36897988, 2023). "c-MYC is a well-known oncogene that is implicated in the development and progression of many human cancers." (PMID 38017538, 2023). "To further test the stemness of NSCLC/PTX-resistant cells, we examined the expression of stemness-associated markers, including KLF4, OCT4, and c-MYC, hallmarks of cancer stem cells." (PMID 38068934, 2023). "Our data from the Bcs1lp.S78G mice with progressive loss of CIII function showed that, similar to cancer cell lines, MYC upregulation precedes eIF2-α phosphorylation." (PMID 37731815, 2023).